CTLA4 (cytotoxic T-lymphocyte associated protein 4)
Diseases named in the same sentence as CTLA4 in open-access papers (continued):
Sharing a sentence is not in itself a finding about the gene and the disease.
metastatic melanoma (continued). "Along this line, the ongoing NIBIT-M4 clinical study, testing the immunologic and clinical efficacy of guadecitabine combined with the anti-CTLA-4 mAb, ipilimumab, in metastatic melanoma patients, will provide further support to the therapeutic potential of epigenetically based immunotherapy." (PMID 30581389, 2018). "We describe the case of a patient with diffusely metastatic melanoma, including brain metastases, who, despite being treated with stereotactic radiosurgery and dual CTLA-4/PD-1 blockade (ipilimumab/nivolumab), developed systemic disease progression and innumerable brain metastases." (PMID 29622046, 2018). "For example, high levels of CTLA-4, PD-1, PD-L1/2, LAG3, and IDO1 that we detected in metastatic melanoma, were many fold times more significantly associated with high cytolytic levels, pointing towards the existence of immunosuppression in these metastatic tumors." (PMID 29515971, 2018). "The combination therapy with anti-PD-1 and anti-CTLA-4 agents is approved by FDA for metastatic melanoma, renal cell carcinoma and microsatellite instability-high (MSI-H) or mismatch repair deficient (dMMR) metastatic colorectal cancer, based on improved overall survival versus either agent alone." (PMID 30400835, 2018). "It is speculated that 131I-5-IPN combined with CTLA-4 or PD-1 inhibitors may be a promising therapeutic direction for patients with metastatic melanoma." (PMID 30537980, 2018). "In a study that compared response of PD-1 monotherapy (nivolumab) with CTLA-4 monotherapy (ipilimumab) in patients with untreated metastatic melanoma, patients receiving PD-1 blockade showed improved progression-free survival (PFS) along with less frequent immune-related adverse effects (irAEs)." (PMID 30497521, 2018). "Furthermore, in a recent phase I trial of patients with metastatic melanoma, bevacizumab enhanced intratumoral lymphocyte infiltration and humoral immune responses in combination with CTLA-4 blockade." (PMID 29207684, 2017). "Current Food and Drug Administration approved immunotherapies for metastatic melanoma include antibody inhibitors of the CTLA-4 checkpoint molecule (ipilimumab) or the PD-1 checkpoint molecule (nivolumab and pembrolizumab), although many others are currently in clinical development." (PMID 28435677, 2017). "Numbers of clinical trials reported that CTLA-4 mAb treatment in patients with metastatic melanoma and prostate cancer could mediate objective clinical regression and enhanced antitumor response by the improvement of effector T-cell activation of patients." (PMID 28099147, 2017). "So far, CTLA4 (cytotoxic T-lymphocyte protein 4; Ipilimumab) and PD-1 (programmed cell death 1; Nivolumab, Pembrolizumab) axis targeting immune checkpoint inhibitors have been approved for the treatment of metastatic melanoma." (PMID 28374234, 2017). "Interestingly, bevacizumab shows synergistic effect with ipilimumab, which blocks CTLA4, improving survival in patients with metastatic melanoma." (PMID 27974353, 2017). "Because severe (grade 3–5) side effects also occurred less frequently in anti-PD-1-treated (13.3%) compared with anti-CTLA-4-treated patients (19.9%), anti-PD-1 treatment is currently the first-line treatment for unresectable or metastatic melanoma in the USA and the EU." (PMID 27847783, 2016). "However, a phase I trial combining BRAFV600E inhibitor vemurafenib with anti-CTLA-4 (ipilimumab) in metastatic melanoma was halted due to severe hepatotoxicity." (PMID 27847783, 2016). "Therefore, blockade of the inhibitory effects of CTLA-4 or combination of NY-ESO-1 vaccination with CTLA-4 blockade can enhance antitumor response in metastatic melanoma patients, resulting in clinical benefits." (PMID 27683579, 2016). "Genomic correlates of response to CTLA-4 blockade in metastatic melanoma." (PMID 27461275, 2016).
metastatic melanoma (continued). "Finally, a recent phase I study in metastatic melanoma patients reported an 18% abscopal response rate, but this is also expected from anti-CTLA-4 treatment alone." (PMID 27847783, 2016). "The anti-CTLA-4 monoclonal antibody ipilimumab (fully human IgG1, Bristol-Myers Squibb) increased the median overall survival (OS) among metastatic melanoma patients in a pooled analysis of phase II and III data and some patients even survived 10 years after treatment." (PMID 27847783, 2016). "Indeed, a high serum level of sIL-2Rα in patients with metastatic melanoma is strongly correlated with poor outcomes from anti-CTLA-4 treatment, which requires concomitant IL-2-mediated immune activation." (PMID 27876012, 2016). "Indeed, monoclonal antibodies blocking either CTLA-4 or PD-1 have recently been approved for the treatment of metastatic melanoma in the United States, Europe and Japan." (PMID 25901287, 2015). "The FDA approval of anti-CTLA-4 for the treatment of metastatic melanoma and of anti-PD-1 for metastatic melanoma and non-small cell lung cancer has engendered new-found awareness among oncologists of the potential antitumor activity of immune checkpoint modulation." (PMID 26605342, 2015). "Recent trials applying immune inhibitory pathway inhibitors such as anti-CTLA-4 and anti-PD-1 agents in metastatic melanoma demonstrated a significantly improved progression free survival in patients and are a testament to the importance of immune inhibitory pathways in cancer pathogenesis." (PMID 26286851, 2015). "In the ever-expanding field of mAbs for cancer, the first phase III trial comparing the PD-1 inhibitor pembrolizumab versus the CTLA4 inhibitor ipilimumab as first-line therapy demonstrated that pembrolizumab was superior in patients with metastatic melanoma according to all of the study endpoints." (PMID 26110058, 2015). "The anti-CTLA-4 mAb ipilimumab is an approved treatment for metastatic melanoma." (PMID 26338962, 2015). "Ipilimumab (Yervoy®), a CTLA-4 mAb, has been approved for treatment of metastatic melanoma." (PMID 25355407, 2014). "Ipilimumab, approved by the US Food and Drug Administration for the treatment of metastatic melanoma, has been the anti-CTLA-4 mAb most extensively investigated, although the molecular mechanisms underlying its anti-tumor activity have not been fully elucidated." (PMID 23634660, 2013). "In patient trials, effective CTL responses to a tumour antigen were generated following vaccination and anti-CD25 Treg depletion in patients with metastatic cancers and improved survival resulted from inclusion of anti-CTLA-4 treatment with immunization for metastatic melanoma." (PMID 23799135, 2013). "Eventually, rational combination of B-RAF inhibitors (e.g., vemurafenib, dabrafenib) with drugs that specifically target one of the molecules (e.g., MEK, c-KIT, or CTLA-4) would further improve the clinical outcome of the patients with advanced/metastatic melanoma." (PMID 23533766, 2013). "The anti-CTLA-4 monoclonal antibody ipilimumab is now registered by the FDA as the first treatment that has shown an overall survival benefit in a randomized phase III study in metastatic melanoma in combination with dacarbazine chemotherapy." (PMID 23626745, 2013). "Confirming the significant role of CTLA-4 signaling in the immunosuppression of cancer patients, the blockage of this molecule in clinical settings by monoclonal antibodies has been able to improve significantly the survival of metastatic melanoma patients." (PMID 23762097, 2013). "Additionally, ipilimumab, an antibody blocking cytotoxic T lymphocyte-associated antigen 4 (CTLA-4) that facilitates T cell activation, was found to provide a benefit in overall survival in individuals with metastatic melanoma." (PMID 23653893, 2013).
metastatic melanoma (continued). "Consistently, CTLA4 blockade with the CTLA4–specific antibody ipilimumabTM leads to increased T cell-mediated effector responses and induces cancer regression in clinical trials of patients with metastatic melanoma." (PMID 22962608, 2012). "However, the recent report that treatment with the immune modulating antibody anti-CTLA4 antibody ipilimumab prolonged survival compared to a gp100 vaccine in patients with previously treated metastatic melanoma should invigorate the field of immunotherapy." (PMID 20875102, 2010). "While up to 20–30% of patients treated with anti-CTLA-4 or anti-PD-1 may experience durable cancer control, ~50% of metastatic melanoma patients treated with the combination of anti-CTLA-4 plus anti-PD-1 experience durable cancer control; however, immune related adverse events remain a problem." (PMID 38187708, 2024). "Despite the failure to generate satisfying clinical outcomes as monotherapy, GM-CSF-secreting tumor vaccines function in a synergistic way with immune checkpoint inhibitors (ICIs) such as Ipilimumab (anti-CTLA-4 antibody) in metastatic melanoma by virtue of its mighty immunostimulatory effects." (PMID 38878186, 2024). "Hence, the anti-CTLA4 antibody ipilimumab (10 mg/kg) plus dacarbazine significantly prolonged overall survival (11.2 vs. 9.1 months; HR 0.72; p < 0.001) compared to dacarbazine alone for patients with untreated metastatic melanoma." (PMID 38539487, 2024). "There have also been reports on the impact of obesity on CTLA-4 treatment, where patients with BMI ≥ 25 (overweight or obese) had significantly improved response rates compared to patients with BMI < 25 (normal or underweight) who received ipilimumab as monotherapy for metastatic melanoma." (PMID 38311726, 2024). "New drugs and drug combinations are being developed to improve the treatment of metastatic melanoma, as researchers have found secondary resistance to existing treatments like tyrosine kinase inhibitors (RTKs), especially those directed at activating BRAF mutations, CTLA4, and PD1 inhibitors." (PMID 39280375, 2024). "Recent studies have revealed that around 40% of patients with metastatic melanoma who underwent PD-1 inhibitor monotherapy experienced positive outcomes, while over 60% of those who underwent standard therapy combined with dual blockade of CTLA-4 and PD-1 showed favorable results." (PMID 37605149, 2023). "However, combined with our present study, we believed that reproductive safety must be considered when checkpoint inhibitors were used during pregnancy, though it was reported that conception and viable twin pregnancy in a metastatic melanoma patient treated with CTLA-4 and PD-1 inhibitors." (PMID 35550500, 2022). "This validation study was undertaken to confirm that early ctDNA kinetics, interpreted using well-defined evaluation criteria, could predict responses to anti-PD1 immunotherapy alone or in combination with anti-CTLA-4 in an independent prospective cohort of metastatic melanoma patients." (PMID 33920470, 2021). "Furthermore, clinical trial results have shown that combining antigen-specific CTLs with ipilimumab (CTLA-4 blockade) is safe as well as effective, and could produce durable clinical responses in patients with metastatic melanoma." (PMID 34207884, 2021). "We tested this hypothesis using a human proteome microarray to identify toxicity-associated autoantibodies in pre-treatment sera from 75 metastatic melanoma patients who received anti-CTLA-4, anti-PD-1, or combination treatment (anti-CTLA-4 and anti-PD-1 together)." (PMID 29606147, 2018).
metastatic melanoma (continued). "The anti-PD-1 antibodies pembrolizumab and nivolumab have shown promising results in patients with metastatic melanoma not harboring the mutation in the B-Raf proto-oncogene (BRAF-mutation) with improved survival rates when compared to the anti CTLA-4 antibody ipilimumab and chemotherapy." (PMID 28430133, 2017). "In a subsequent study, same authors hypothesized that in patients with metastatic melanoma, CTLA-4 blockade might enhance the antitumor effect of IL-2, since IL-2 stimulates T-cell growth, but has also been implicated in the expansion of Tregs that express cell-surface CTLA-4." (PMID 24594636, 2014). "Indeed, both ipilimumab (a fully human monoclonal antibody that blocks CTLA-4 to promote antitumor immunity) and vemurafenib (a potent inhibitor of mutated V600E BRAF) have been recently approved in Europe and the US for the treatment of metastatic melanoma." (PMID 23402397, 2013). "Two metastatic melanoma patients underwent [18F]CFA-PET/computed tomography (CT) before and 2–4 weeks after the onset of combined CIT (anti-PD1 mAb + anti-CTLA4 mAb)." (PMID 41495426, 2026). "Another study on metastatic melanoma patients showed that IL-21-induced polyclonal CTL, in combination with CTLA4 blockade, controlled refractory metastatic melanoma." (PMID 40376002, 2025). "Current cornerstone treatments for metastatic melanoma include immune checkpoint modulators, such as LAG3 inhibitors, pembrolizumab, nivolumab, and ipilimumab targeting CTLA-4, and PDL1." (PMID 39974235, 2025). "Our results suggest that high plasma sCD27 levels predict poorer efficacy of anti-PD1 monotherapy in metastatic melanoma, justifying therapeutic escalation with a combination of anti-PD1 and anti-CTLA-4." (PMID 40148586, 2025). "Ipilimumab, a human CTLA-4 antibody, was approved by the FDA in 2011 to treat unresectable or metastatic melanoma." (PMID 40636119, 2025). "Ipilimumab, a human anti-CTLA-4 monoclonal antibody (mAb), is the first ICI approved by the US Food and Drug Administration (FDA) as a monotherapy for metastatic melanoma." (PMID 39354625, 2024). "TERT promoter mutations have been discussed as potential prognostic factors in metastatic melanoma and as potentially predictive most recently under BRAF/MEK and anti-CTLA4 therapy." (PMID 37418389, 2023). "The 5-year survival rate of metastatic melanoma is 31–34% with targeted combined BRAF–MEK inhibitor therapy, 42–43% with anti-PD1 inhibitor therapy, and 46–57% with combined anti-CTLA-4 and anti-PD-1 therapy." (PMID 38202181, 2023). "In retrospective studies performed among metastatic melanoma patients treated with anti-PD-1, anti-CTLA-4 or anti-CTLA-4+anti-PD-1 the baseline serum S100B level proved to be independent predictor of primary resistance to therapy and overall survival." (PMID 37664072, 2023). "Immune checkpoint inhibitors (ICI) against CTLA-4 and PD1 have initiated a breakthrough in the treatment and improved prognosis of patients with metastatic melanoma." (PMID 36979727, 2023). "This patient had been diagnosed with metastatic melanoma, and all relevant treatment options had been exploited, including immune checkpoint inhibition (ICI) with anti-PD1 and the combination of anti-CTLA4 plus anti-PD-1." (PMID 38067230, 2023). "After several clinical trials proved the effectiveness of ipilimumab, a monoclonal antibody that targets CTLA-4, the FDA authorized the inclusion of this antibody in the treatment of patients with unresectable or metastatic melanoma." (PMID 38139110, 2023). "In previous studies, we identified CTLA4 methylation as a predictive biomarker for anti-PD-1 and anti-CTLA-4-directed therapy in patients with metastatic melanoma and metastatic clear cell renal cell carcinoma." (PMID 37259155, 2023).
metastatic melanoma (continued). "For example, there is evidence that anti-CTLA-4 and anti-PD-1 therapy results in the upregulation of VISTA in patients with localized prostate adenocarcinoma and metastatic melanoma during treatment forming a basis to test such combination therapies." (PMID 36891296, 2023). "The anti-CTLA-4 monoclonal antibody ipilimumab was the first checkpoint inhibitor (CPI) to receive Food and Drug Administration approval for the treatment of metastatic malignant melanoma." (PMID 36089578, 2022). "Metastatic melanoma was the first US Food and Drug Administration (FDA)-approved indication for the ICI ipilimumab, a monoclonal antibody against CTLA-4, and this approval was granted over a decade ago." (PMID 35876944, 2022). "BRAFi/MEKi as second-line therapy provides higher ORR, as in a large retrospective analysis, metastatic melanoma patients resistant to PD-1 who were treated with PD-1 + CTLA4 achieved an ORR of 31%, while among those treated with CTLA4 monotherapy only 12%." (PMID 35456332, 2022). "Simultaneously, the stool was obtained from a group of 42 patients with metastatic melanoma treated with ICI (38 = anti-PD-1, 4 = anti-CTLA-4), and the GM was analysed using a combination of 16S rRNA sequencing and shotgun metagenomic sequencing." (PMID 35876944, 2022). "In 2014, after the first CTLA-4 monoclonal antibody was approved by the US FDA, the PD-1 monoclonal antibody was again approved by the FDA for the treatment of metastatic melanoma." (PMID 36591239, 2022). "Following CTLA-4 treatment, the FDA approved the inhibition of programmed death-1 (PD-1) and its ligand PD-L1 as immune checkpoint inhibitors for metastatic melanoma and lung cancers." (PMID 35936003, 2022). "Ipilimumab is a human anti-CTLA-4 monoclonal antibody (mAb) that blocks CTLA-4 and its ligands (CD80/CD86) with demonstrated efficacy in metastatic melanoma." (PMID 35428347, 2022). "For example, anti-CTLA4 therapy is the first immunotherapy approved by FDA (Food and Drug Administration), which has achieved significant results in metastatic melanoma." (PMID 35444953, 2022). "Since the completion of this clinical trial, PD-1 inhibitors, either as single agents or in combination with a CTLA-4 or a LAG-3 inhibitor, have replaced ipilimumab monotherapy as the standard of care for metastatic melanoma." (PMID 36089578, 2022). "A Stage IV metastatic melanoma patient with tumor highly expressive of the 12-CK score and TLS enrichment demonstrated a more than 30 month partial response to ipilimumab (CTLA-4 antagonist)." (PMID 34267760, 2021). "Ipilimumab, an anti-CTLA-4 antibody, was the first checkpoint inhibitor approved by the Food and Drug Administration (FDA) in 2011 for the treatment in metastatic melanoma." (PMID 34445385, 2021). "In a case report, the combination of anti-CTLA-4 and anti-RANKL was used in a rapidly progressing metastatic melanoma patient with aggressive and symptomatic bone metastases, and no obvious residual lesion was found 62 weeks after diagnosis." (PMID 34877360, 2021). "Therefore, the predictive value of MAP2K1/2 mutation in metastatic melanoma might be specific to anti-CTLA-4 therapy, rather than anti-PD-1/L1 therapy." (PMID 35069558, 2021). "Anti-CTLA-4 and anti-PD-1 immune checkpoints inhibitors (ICI) have revolutionized the treatment of metastatic melanoma patients, leading to durable responses." (PMID 33810032, 2021). "In 2011, ipilimumab (anti CTLA4) gained Food and Drug Administration (FDA) approval for treatment of metastatic melanoma." (PMID 34207884, 2021). "The human monoclonal anti-CTLA-4 IgG1 antibody Ipilimumab (Yervoy, MDX-010) was FDA approved in 2011 for the treatment of metastatic melanoma." (PMID 34445385, 2021). "So far, the most effective treatment for metastatic melanoma is immune checkpoint inhibitors, such as anti-PD1, PD-L1/2, and CTLA4 antibodies." (PMID 34804126, 2021).